BEND7 (BEN domain containing 7)
Synonyms: C10orf30; FLJ40283
Tractability: PROTAC: UniProt records ubiquitination sites on it.
Gene: Protein-coding gene on chromosome 10 (13,438,484 to 13,529,237, reverse strand). Ensembl gene ENSG00000165626.
Subcellular location (Human Protein Atlas): Nucleoli fibrillar center; Nucleoplasm; Vesicles
Gene Ontology:
Molecular function: protein binding; DNA binding
Cellular component: extracellular exosome
Genetic constraint (gnomAD): Loss-of-function variants: 26 observed, 42.84 expected, observed/expected ratio (o/e) 0.61, 90% interval 0.44 to 0.84. The upper end of that interval is the gene's LOEUF score, 0.84, which puts it in group 3 of 6, group 1 being the genes least tolerant of losing a copy. Missense variants: 422 observed, 458.32 expected, observed/expected ratio (o/e) 0.92, 90% interval 0.85 to 1. Synonymous variants: 157 observed, 172.02 expected, observed/expected ratio (o/e) 0.91, 90% interval 0.8 to 1.04.
Homologues: Orthologues: pig BEND7 (90% identical), mouse Bend7 (87% identical), tropical clawed frog bend7 (56% identical), zebrafish bend7 (46% identical).
Diseases named in the same sentence as BEND7 in open-access papers:
BEND7 is named in the same sentence as 2 diseases in open-access papers, as found by Europe PMC text mining. Sharing a sentence is not in itself a finding about the gene and the disease.
BEND7 shares sentences with these, for which no sentence is quoted: entropion (1 paper); glioma (1).